INS (insulin)
Diseases named in the same sentence as INS in open-access papers (continued):
Sharing a sentence is not in itself a finding about the gene and the disease.
cancer (continued). "Transcripts encoding for metalloproteinases, typical drivers of cancer invasion, metastasis, and angiogenesis, also followed a similar pattern of response to insulin stimulation." (PMID 34831367, 2021). "The effect of metformin, sulfonylureas and insulin on the risk of various cancers have been analysed and derivatives of sulfonylurea and insulin exposure have been documented to increase the risk of cancer." (PMID 34535145, 2021). "Insulin resistance has been associated with type II diabetes and obesity, where increased insulin levels are shown to correlate with increased risk of several cancer types." (PMID 34191793, 2021). "Nevertheless, EHBP1 has already been associated with cancer and is required for the insulin-mediated translocation of glucose transporter type 4." (PMID 34715892, 2021). "In a case–control study for investigating the association between antidiabetic medication and cancer risk over 20 years, it was reported that, only pioglitazone and insulin analogues as antidiabetic drugs were associated with cancer risk." (PMID 34535145, 2021). "Physical activity can reduce the risk of cancer by improving insulin sensitivity and reducing fasting insulin levels, decreasing oxidative stress and enhancing DNA repair mechanisms (WCRF/AICR 2018b)." (PMID 34452552, 2021). "Experimental and molecular epidemiologic studies indicate important roles for dysregulated sex hormone metabolism, adipose tissue-derived inflammation, and alterations in insulin signalling in mediating the adiposity and cancer associations." (PMID 33926456, 2021). "In several studies, a significant association betweenthe risk of cancer and use of exogenous insulin or upregulation of IR was reported." (PMID 34308576, 2021). "These omega-3 fatty acids are thought to prevent cancer development by altering gene expression, oestrogen metabolism, and by causing improved insulin sensitivity and reduced inflammation." (PMID 33946913, 2021). "Although no direct tumorigenic properties have been described, two studies have pointed out high risk of cancer in individuals treated with sulfonylureas compared to those treated with glyburide or insulin." (PMID 34680546, 2021). "For example, based on clinical observations and the known molecular mechanisms of insulin action, the benefits and risks of initiating and continuing insulin therapy in terms of cancer risk should always be considered." (PMID 33562380, 2021). "We explore the possible biologic mechanisms underpinning the associations between these lifestyle factors and cancer incidence, including effects on endogenous sex steroids and metabolic hormones, insulin sensitivity, and chronic inflammation." (PMID 32741068, 2021). "Retrospective studies showed that DM individuals receiving MET had a low risk of developing cancer, while patients receiving sulphonylureas and insulin had an expanded cancer frequency and mortality rates." (PMID 33440701, 2021). "Regarding usage of insulin, various reports and data related to cancer risk are there but still inconclusive as plethora of factors are needed to study for a meaningful comparison." (PMID 34535145, 2021). "A possible explanation of a relationship between height and cancer was that the several genetic variants related to the insulin-growth factor signaling pathway are also related to height." (PMID 34611257, 2021). "Reduced inflammation, increased insulin sensitivity, and protection against cancer are shared between humans and mice with GH/IGF1 deficiency." (PMID 34118183, 2021). "The anti-cancer effects of metformin have been postulated to be associated with low insulin level subsequent to inhibition of hepatic gluconeogenesis." (PMID 33198356, 2020). "The first is a direct anti-cancer mechanism that is unrelated to insulin, and the second is an indirect mechanism associated with insulin." (PMID 33198356, 2020).
cancer (continued). "In a 15-year mortality study, individuals in the highest quintile of serum insulin had a 62% higher risk of cancer mortality and a 161% higher risk of gastrointestinal cancer mortality." (PMID 32983729, 2020). "KEGG analysis showed that insulin signaling pathway, glycine, serine and threonine metabolism, pathways in cancer, lysosome, and apoptosis was associated with hypertensive." (PMID 33176720, 2020). "DM is caused by abnormalities of both insulin and glucose, and both are related to cancer cell proliferation." (PMID 33255227, 2020). "Some epidemiologic studies have highlighted concerns for an increased risk of cancer among insulin glarine user." (PMID 32156062, 2020). "Mounting evidence has additionally shown that cancer prognosis is affected by insulin and IGF-1 circulating levels, independently of cancer risk." (PMID 32351453, 2020). "Relative to the unhealthy score, the healthy one scored more negatively foods rich in refined carbohydrates, which are supposed to be implicated in cancer risk through energy metabolism, insulin, and insulin-like growth factor (IGF-1) upregulations." (PMID 32640737, 2020). "Metformin improves blood glucose levels by increasing insulin sensitivity and reducing gluconeogenesis by the liver, which helps in diminishing insulin production and therefore decreases the risk of cancer development." (PMID 32717852, 2020). "The IGF1/insulin pathway regulates growth in normal tissues and is associated with cancer development and reduced cancer survival rates." (PMID 33260481, 2020). "In a large German study, a higher cancer incidence was associated with administration of glargine compared to human insulin." (PMID 33585194, 2020). "High levels of insulin and c-peptide have been reported to be associated with poor survival outcomes in patients diagnosed with cancer." (PMID 33198356, 2020). "As diabetes is known to be a high-risk factor for developing cancers, c-peptide has been used as a diagnostic marker for insulin in the identification of risk factors for cancer." (PMID 32375229, 2020). "For example, the hyperactivation of the phosphatidylinositol-3 kinase and AKT (PI3K-AKT) transduces the signal from the hormone insulin to drive glucose uptake and is one of the most frequently mutated pathways in cancer." (PMID 32854444, 2020). "New long-acting insulin, known as degludec, has been developed, and it will be important to analyze the effects on cancer risk, if any." (PMID 32498358, 2020). "Fasting insulin in the upper quartile conferred a 37% increased risk for total mortality among cancer patients, adjusting for age and ethnic origin (95% CI 0.94–2.00, P = 0.097) compared with that of the lower quartiles." (PMID 32153503, 2020). "SU are secretagogues for insulin and are reported to be associated with a higher risk of cancer development." (PMID 32498358, 2020). "Metformin, which decreases systemic insulin levels, is reported to reduce the cancer risk and cancer-related mortality, although recent papers are challenging the results of previous studies." (PMID 33186403, 2020). "Fourth, whole grains have antioxidant and anti-inflammatory properties and it can improves blood sugar response and reduces insulin resistance, thereby reducing the risk of cancer." (PMID 32493399, 2020). "There is no robust evidence describing the influence of the type of production of insulin on the development of SPMs or risk of cancer." (PMID 33585194, 2020). "Under these conditions, the chronically increased insulin levels associate with increased cancer risk and to parallel increase levels in IR and Insulin-like Growth factor I (IGF1R)." (PMID 33266015, 2020). "In conclusion, these results indicate that the correlation between HLA-G genotypes, and specifically those containing the 14-bp INS allele, and pregnancy loss or susceptibility to specific types of cancer has been achieved." (PMID 32733439, 2020).
cancer (continued). "As such, the increase in insulin associated with both of these conditions has been cited as a factor in the development of cancer." (PMID 32742493, 2020). "There are several explanations for the causal role of insulin, directly or indirectly, in cancer incidence and risk of mortality." (PMID 32705315, 2020). "This is particularly relevant in those conditions where they are co-expressed, such as during the pathogenic process linked to insulin-resistant states and cancer." (PMID 33266015, 2020). "In our analyses, only marker rs4197 (FADD gene) was associated to GC development as follows: INS/DEL genotype of rs4197 increasing in about 2-fold the chances of developing this type of cancer (P = 0.046; OR = 1.940; 95%CI = 1.011–3.725)." (PMID 33076854, 2020). "People exposed to starvation have a high risk of developing cancer later in life, and prior studies have shown these individuals have high insulin and cholesterol levels and are sensitive to glucose." (PMID 32857726, 2020). "In fact, evidence suggests that cancer prognosis is affected by insulin and IGF-1 circulating levels, independently of cancer risk." (PMID 32351453, 2020). "The insulin signaling pathway is an important pathway, and its components are associated with many critical signaling pathways associated with cancers, immune systems, and more." (PMID 33552973, 2020). "Greater physical activity has been associated with lower circulating levels of insulin and insulin-like growth factors, which promote cellular proliferation in breast and colorectal tissue and have also been linked to development of cancers at these sites." (PMID 32001714, 2020). "Apart from dwarfism, such individuals have an increased sensitivity to insulin (reducing the risk of type-2 diabetes and reduced rates of all cancers." (PMID 31636602, 2019). "In particular, overexpression of IR and its interaction with circulating insulin is a hallmark of many cancers." (PMID 30895469, 2019). "In the future, the relationship of INS rs689 T > A polymorphism with cancer risk should be explored in more case‐control studies." (PMID 31211453, 2019). "These SCFA can modify epigenetic landmarks (i.e., histone acetylation) and modulate the expression of genes related to pathways associated with cancer, lipid metabolism, glucose homeostasis, and insulin sensitivity, among others." (PMID 31615571, 2019). "On the other hand, insulin and insulin secretagogues have been associated with a 62% increase and a 161% increase of incidence and cancer-related mortality." (PMID 30774659, 2019). "Recent studies showed that patients treated with sulfonylureas or exogenous insulin have a higher risk of cancer." (PMID 31284513, 2019). "Third, the oral delivery of insulin under development for clinical use requires more intensive and cautious evaluation of cancer risk, especially of cancer involving the gastrointestinal tracts." (PMID 31354621, 2019). "Calorie-dense diets, including those that are high in fat and sucrose, have been shown to blunt insulin sensitivity, increase the risk for cardiovascular disease, and increase the incidence of certain types of cancer." (PMID 31484384, 2019). "The published RCT ORIGIN explore effect of glargine insulin on cancer, showed that insulin glargine have a neutral association with overall and cancer-specific outcomes, including cancer-specific mortality." (PMID 31555212, 2019). "This is the first reported case of NICTH caused by co-secretion of insulin from multiple primary carcinomas." (PMID 29166433, 2019). "Increased glucose consumption is a hallmark of most cancer cells, and increased blood glucose and insulin levels observed in type 2 diabetes are associated with poor cancer prognosis." (PMID 29805774, 2018).
cancer (continued). "McTiernan suggested physical activity to be linked to cancer protection through exercise-dependent reductions in cancer risk factors, such as sex hormones, insulin/insulin like growth factor (IGF), and inflammatory markers." (PMID 29910314, 2018). "Rho GTPase-activating protein encoded by the ARHGAP22 gene is known to be involved in insulin response mechanisms regulating endothelial cell migration and cancer metastasis." (PMID 30266984, 2018). "The insulin antagonist ImpL2 causes cachexia in Drosophila, and IGFBPs have been implicated in mammalian cancers." (PMID 29592890, 2018). "Insulin was studied for its anti-lipolytic effects in 138 patients with advanced GI malignancies and cancer cachexia (weight loss 2–3% of baseline and albumin < 36 g/L)." (PMID 30482179, 2018). "In NASH-HCCs, the 16 mutated genes involved in insulin signaling included insulin receptor (Insr) and some other well-known cancer-related genes (Mtor, Hras1, Akt3, etc), with Mtor and Hras1 recurrently mutated." (PMID 30367044, 2018). "As a high level of IGF-1 and dysregulation of IGF-1R signaling are also associated with tumor development, it is necessary to evaluate the administration level of native insulin or insulin analogue in terms of reducing cancer risk." (PMID 30154386, 2018). "Cancer-associated muscle wasting is associated with metabolic impairments, including insulin insensitivity." (PMID 29723245, 2018). "Further, various gene sets reflecting different cancer associated pathways and insulin related signaling were enriched in the ‘Cancer’ cluster." (PMID 30404611, 2018). "Diabetic patients possess a higher risk of developing cancers than healthy patients, which is partly due to increasing levels of circulating growth factors, such as insulin or insulin growth factor 1 and 2 (IGF-1 and 2)." (PMID 30186236, 2018). "Metabolite measures associated with cancer preventive behaviors included biomarkers of inflammation, insulin sensitivity, as well as cardiometabolic risk; aberrations in lipid classes, lipid concentrations in HDL, VLDL, TG subclasses, and lipid particle size." (PMID 30390014, 2018). "Conversely, data from observational studies indicate an increased cancer risk associated with the use of exogenous insulin." (PMID 28978007, 2017). "Higher insulin and c-peptide levels have been associated with poorer outcomes in cancer patients, and metformin has been shown to be effective at reducing insulin levels, even in non-diabetic patients." (PMID 28444639, 2017). "On the other hand, T2DM patients who were treated with metformin, an insulin sensitizer, showed a reduced risk of cancer (odds-ratio for any exposure to metformin was 0.79)." (PMID 28424632, 2017). "This review will focus on the mechanisms that link insulin resistance to cancer risk and will discuss the possible clinical implications of PPAR-γ agonists in cancers with dysregulated IGF axis." (PMID 28275367, 2017). "In the nonuser group, where increased CRC risk was found, the mediation effect of insulin level on this SNP–cancer association was strong (> 80%)." (PMID 29023587, 2017). "Epidemiological studies suggested that a high insulin level was associated with increased occurrence and mortality of cancers." (PMID 28409158, 2017). "In muscle tissue, the genes upregulated in YY were mainly associated with transcriptional misregulation in cancer, signaling pathways regulating pluripotency of stem cells, and the insulin signaling pathway." (PMID 28877211, 2017). "Accordingly, T2DM patients who used insulin analogs such as glargine exhibited a high risk of cancer in a dose-dependent manner (adjusted hazard ratio was 1.1, 1.2, and 1.3 for daily doses of 10, 30, and 50 U, respectively)." (PMID 28424632, 2017). "Circulating insulin levels, higher than average, have been shown to be associated with increased cancer growth and mortality." (PMID 29075616, 2017).
cancer (continued). "Comparisons of cancer incidence by cumulative treatment time using active comparators showed no consistent differences in the cancer risk for insulin glargine or insulin detemir use relative to that of human insulin use." (PMID 28573394, 2017). "When comparing longer cumulative treatment time on insulin glargine with time on human insulin, we found a decreased risk for some cancers and treatment durations." (PMID 28573394, 2017). "No trend with cumulative treatment time for insulin glargine relative to human insulin was observed in risk for any of the ten studied cancer types." (PMID 28573394, 2017). "Medications that acting through an increase of the circulating levels of insulin (including insulin and its analogues, insulin secretagogues) have been reported to be associated with an increased risk of cancer." (PMID 28591216, 2017). "KEGG pathway enrichment analysis further suggested that those genes were associated with cancer and insulin secretion." (PMID 28969062, 2017). "The details regarding tumor necrosis factor α, interleukin 1β and its receptor antagonist, and interleukin 6 determination from plasma, their association with cancer outcomes and use of insulin secretagogues has been previously reported." (PMID 28275673, 2017). "Glucose and insulin levels are closely linked, which makes it difficult to separate the association, although they influence the cancer development through different pathways." (PMID 29233100, 2017). "In contrast, carriers of the AKT1 rs2494740 T allele had an increased risk of CRC among E+P users, with about 50% of this SNP–cancer association explained by insulin level." (PMID 29023587, 2017). "Clinical and basic scientists should be aware of this information and conduct future investigations to clarify the mechanisms behind the relationship between cancer risk and use of insulin analogs." (PMID 28424632, 2017). "We found no persistent differences in the risk for ten specific cancers and any cancer, when comparing use of the insulin analogues insulin glargine or insulin detemir vs human insulin." (PMID 28573394, 2017). "One meta-analysis found that diabetic patients treated with insulin had an increased cancer risk compared to non-insulin-treated diabetics, while another study reported an inconsistent impact of insulin on cancer incidence." (PMID 27648070, 2016). "In a study conducted using data from CPRD, insulin monotherapy was reported to be associated with a significantly higher risk of MACE, cancer, or death when compared with insulin in combination with metformin (1.51, 1.28–1.78)." (PMID 27152598, 2016). "The adjusted hazard ratio (95% confidence interval) associated with insulin use was 1.161 (1.052–1.281) for cancer death and 1.469 (1.413–1.526) for non-cancer death." (PMID 27906989, 2016). "It has also been reported that obese insulin-resistant individuals had elevated risk of cancer mortality (HR = 1.52) compared to obese insulin-sensitive individuals (HR = 1.04)." (PMID 27338371, 2016). "This is why insulin administered for the management of DM type I and insulin secretagogues (sulfonylureas) have been associated with an increased incidence of cancer." (PMID 27164115, 2016). "In many cancers, the phosphatidylinositol 3′-kinase pathway is upregulated, either by elevated levels of insulin or IGF or by loss-of-function mutations of the tumor suppressor PTEN." (PMID 28018856, 2016). "The deregulation of fat metabolism derived from excessive insulin, glucose, and lipid promotes cancer-causing inflammatory signaling and oxidative stress, which eventually triggers the uncontrolled hepatocellular proliferation." (PMID 27703473, 2016). "Insulin-sensitizers antiangiogenetic effects reduce DNA damage and mutation rates offering an explanation for the reduced risk of cancer seen in metformin users across several epidemiological studies." (PMID 27725832, 2016).